SNORD27 (small nucleolar RNA, C/D box 27)
Synonyms: U27; RNU27
Gene: Small nucleolar RNA gene on chromosome 11 (62,855,012 to 62,855,083, reverse strand). Ensembl gene ENSG00000275996.
Gene Ontology:
Biological process: RNA processing
Cellular component: nucleolus
Homologues: Orthologues: chimpanzee SNORD27 (100% identical), macaque SNORD27 (96% identical), dog SNORD27 (92% identical), pig SNORD27 (88% identical), rabbit SNORD27 (85% identical), rat Snord27 (83% identical), guinea pig SNORD27 (81% identical), mouse Gm24452 (76% identical), tropical clawed frog SNORD27 (72% identical). Paralogues in human: SNORD27 (86% identical).
Diseases named in the same sentence as SNORD27 in open-access papers:
SNORD27 is named in the same sentence as 4 diseases in open-access papers, as found by Europe PMC text mining. Sharing a sentence is not in itself a finding about the gene and the disease. The quoted sentences say what the papers report.
infection (1 paper, 2022). The state of being infected such as from the introduction of a foreign agent such as serum, vaccine, antigenic substance or organism. "The silencing of SNORA/Ds encoded within RPS11 (SNORD35B), SNHG3 (SNORA73A, SNORA73B), and SNHG1 (SNORD22, SNORD25, SNORD26, SNORD27, SNORD28, SNORD29, SNORD30, SNORD31) inhibited infection with influenza A virus." (PMID 36430145, 2022).
SNORD27 also shares sentences with these, for which no sentence is quoted: cancer (1 paper); peripheral T-cell Lymphoma (1); viral infections (1).